IFITM3 (interferon induced transmembrane protein 3)
Diseases named in the same sentence as IFITM3 in open-access papers (continued):
Sharing a sentence is not in itself a finding about the gene and the disease.
infection (continued). "We showed that the expression of placental IFITM1 and IFITM3 transcripts was upregulated in women with severe infection when compared to women with asymptomatic/mild disease or to negative controls." (PMID 34257394, 2021). "The results showed that exosomes derived from macrophages RAW264.7 contained a high abundance of IFITM3 in a time-dependent manner, reaching a maximum at 24 h post-infection." (PMID 33816587, 2021). "KD of IFITM2 and, to a lesser extent, IFITM3 enhanced the number of S/ACE2 PLA foci after infection of Calu-3 cells with genuine SARS-CoV-2." (PMID 34321474, 2021). "Using virus-like particles expressing the envelope proteins of each respective virus, IFITM1, IFITM2 and IFITM3 were all able to inhibit infection compared with controls." (PMID 34020727, 2021). "A549 IFITM1/2/3 KO - ACE2 cells stably expressing IFITM3 constructs were used for the infection studies." (PMID 34981045, 2021). "IFITM3 KO mice also displayed higher levels of lymphocyte and macrophage recruitment to sites of infection, as judged by CD3e and F4/80 staining of infected tissues, respectively." (PMID 34404769, 2021). "More specifically, IFITM1—interferon-induced transmembrane protein 1, IL21R—interleukin 21 receptor and IFITM3—the interferon-induced transmembrane protein 3 (IFITM3), were overexpressed, as observed after infection with precHP viruses." (PMID 34835129, 2021). "For this, A549 cells transfected with the siRNAs and infected with PR8 as above were harvested at 0 h, 6 h, 12 h and 24 h post-infection, and viperin, IFITM3 and ISG15 polypeptides were detected by western blotting." (PMID 35095845, 2021). "IFITM3 is a host antiviral restriction factor that limits cellular infection with multiple notable viral pathogens and is especially crucial for the innate immune response against influenza virus." (PMID 33013775, 2020). "IFITM3 has also been demonstrated to affect severity of infection and improve the host cellular defenses against viruses." (PMID 33240681, 2020). "Since our results showed that PRRSV was transported to endosomes and lysosomes at the beginning of infection, the subcellular localization of IFITM3 was further determined." (PMID 32999030, 2020). "Since host genetic polymorphisms have been demonstrated to be associated with vulnerability to human infection, in this study five candidate genes—ACE2, TMPRSS2, CD209, IFITM3, and MUC5B—were selected based on their relevance to the current pandemic." (PMID 33101356, 2020). "During influenza A infection of human airway epithelial cells, IFITM3 was shown to clusters on virus-containing endosomes and lysosomes within few hours post-infection, indicating its role in the early phase of viral entry." (PMID 32595654, 2020). "Both IFITM1 and IFITM3 were upregulated in the sampled tissues after DTMUV infection, especially the cecum and cecal tonsil, where DTMUV was intensively located, indicating that DTMUV is responsible for the high expression levels of goose IFITM1 and IFITM3." (PMID 32641107, 2020). "Since virions from virus-producing cells in the presence of IFITM3 exhibited decreased infectivity, we evaluated the antiviral effects of IFITM3 in different infection modes." (PMID 32999030, 2020). "We previously found that IFITM3 protein restricts vaccinia virus (VACV) infection by interfering with virus binding and entry in a low pH-dependent manner, and VACV can also inhibit IFITM3 translation." (PMID 33329509, 2020). "For this, we examined the percent of infected cells in control, IFITM3-rel, and IFITM3-high cells by E-protein staining at 24 h post-infection." (PMID 32370187, 2020). "Previous study showed that mice treated with AmphoB developed more severe symptom upon infection by mild IAV isolate, similar to animals deficient in IFITM3." (PMID 32602823, 2020).
infection (continued). "This scenario is illustrated by the loss of IFITM3 resistance in transmitted founder HIV-1 strains, which mutate Env in order to resist autologous antibodies as infection progresses." (PMID 30935048, 2019). "To unravel the distribution pattern of IFITM3 in A549 cells at early stages of infection, we made use of super-resolution microscopy." (PMID 31212878, 2019). "We made the observation that Rab11-positive vesicles loaded with IFITM3 often carried IAV NP early during infection." (PMID 31212878, 2019). "Most findings about the antiviral action and localization of IFITM3 are based on studies using expression plasmids creating an over-expression and/or focusing at the late stages of infection (>12 h post-infection)." (PMID 31212878, 2019). "As expected, we found that IFITM3 significantly inhibited infection by influenza A/WSN/1933 (H1N1) virus during single-cycle replication at 12 hpi, and continued to inhibit during multi-cycle replication at 48 hpi." (PMID 31682641, 2019). "We observed a highly significant increase of IFITM3 cluster co-localization with early endosomes at 1 h p.i., which was subsequently lost in the course of infection." (PMID 31212878, 2019). "Blocking IFNα with a neutralizing antibody during the IAV infection of A549 cells resulted in increased infection rates, and a concomitant minimal increase of the IFITM3 signal." (PMID 31212878, 2019). "A549 cells expressing chicken IFITM3 resisted infection by several luciferase-expressing pseudotyped influenza viruses (H1, H5, H7, and H10)." (PMID 30634569, 2019). "Chicken DF-1 fibroblasts overexpressing IFITM3 resisted infection by A/WSN/1933 (H1N1) compared to controls, while IFITM3 silencing in DF-1 cells rendered them more susceptible to the same infection." (PMID 30634569, 2019). "After 44 h, the level of HSV infection (MOI of 0.01) in IFITM1-expressing A549 cells was 36.6%, compared to 75.5% and 58.1% for IFITM2 and IFITM3, respectively, and 75.1% infection of control empty vector-transduced cells." (PMID 30567988, 2019). "A similar induction of IFITM3 clusters was also observed upon infection with the IAV strain A/Regensburg/D6/2009 (R/D6/2009, H1N1), but this occurred with slower kinetics." (PMID 31212878, 2019). "Cells infected with IAV HK/1/68 were fixed at 1–6 h post infection (h p.i.), stained with anti-IFITM3 and subjected to confocal and STED microscopy (resolution < 50 nm) of the same region." (PMID 31212878, 2019). "Representative images and fluorescence traces show co-trafficking of a LASV particle within an IFITM3+ endosome until fusion occurs around 14 min post-infection." (PMID 30640957, 2019). "IFITM3 appears to act early in the infection, but its mechanism of action and potential interactions with incoming IAV structures are not yet defined." (PMID 31212878, 2019). "IFITM3 cluster formation started at 2-3 h post infection and increased over time to finally coat IAV-containing endosomal vesicles." (PMID 31212878, 2019). "Taken together, our findings provide the first evidence of exogenously expressed IFITM3 protein restricting infection of an enveloped DNA virus, thus expanding their antiviral spectrum." (PMID 29503647, 2018). "In vivo studies in IFITM3 knockout mice demonstrate the critical role of IFITM3 in restricting infection and reducing disease severity of infection by IAV, WNV, Chikungunya virus and Venezuelan equine encephalitis virus, and respiratory syncytial virus." (PMID 30687247, 2018). "In IFNα2b-treated cells, the percentages of infection were significantly suppressed in both HeLa and 293T cells, and knockdown of IFITM3 slightly increased the VTT infection (gray bars)." (PMID 29503647, 2018). "First, we observed that the expression of endogenous IFITM3 was downregulated after infection with VACV but upregulated by IAV strains, such as H5N1 or H9N2 (data not shown)." (PMID 29503647, 2018).
infection (continued). "In vivo, subcutaneous infection with West Nile virus induced increased lethality in IFITM3 KO mice compared to that in WT mice." (PMID 30662816, 2018). "IFITM3 also protects resident memory CD8 T cells from infection and death in the lung during secondary influenza virus infections." (PMID 30662816, 2018). "The discovery of the importance of the rs34481144-A SNP in controlling IFITM3 levels [65••] should facilitate the study of IFITM3 in additional human infections in diverse populations." (PMID 30662816, 2018). "For example, only a limited number of the viruses restricted by IFITM3 in vitro have been studied in IFITM3 KO mice and even fewer infections have been examined in humans." (PMID 30662816, 2018). "Studies using murine infection models have highlighted a critical role for IFITM3 in restricting viral pathogenesis in vivo." (PMID 28240600, 2017). "Using DF-1 cell system, we found that knockdown of endogenous IFITM1 and IFITM3 by short hairpin RNA (shRNA) markedly enhanced ATMUV infection in host." (PMID 28473814, 2017). "Using the MCMV model of infection, we determined that murine IFITM3 is a critical checkpoint regulator of herpesvirus-induced immune pathology during acute and chronic infection in vivo." (PMID 28240600, 2017). "Genes such as Ifi27l2a, which regulate immune cell influx, and Ifitm3, which has antiviral function, were upregulated in both V3000 and V3034 infection suggesting there role in antiviral response during infection with VEEV." (PMID 28446152, 2017). "Another piece of evidence in support of IFITM proteins as membrane remodelers is the finding that amphotericin B, an antifungal compound known to enhance membrane fluidity, counteracts the activity of IFITM3 to render cells permissive to infection." (PMID 29162141, 2017). "That is, HA variants which drive fusion at higher pH (less acidic) are more resistant to the block by IFITM3, suggesting that evasion of more acidic, late endosomes (where IFITM3 resides in most cell types) enables infection." (PMID 29162141, 2017). "The beneficial impact of anti–IL-6R treatment was reduced at later time points of infection in both WT and Ifitm3–/– mice." (PMID 28240600, 2017). "We tested each of these aspects of the SFV entry pathway to determine the stage at which IFITM3 restricts infection." (PMID 27219333, 2016). "All these results suggest that IFITM3 is an important control factor under natural infection of HTNV." (PMID 28096800, 2016). "That IFITM3 can restrict SFV infection by fusion at the cell surface equivalently to IFITM1 suggests that IFITM3 has greater antiviral potency against SFV." (PMID 27219333, 2016). "Overall, despite low levels of cell surface expression, IFITM3‐HA inhibited SFV infection by fusion at the plasma membrane to a similar or greater extent than IFITM1‐HA." (PMID 27219333, 2016). "It is therefore interesting that IFITM3 seems to be able to inhibit infection by cell surface fusion to an equivalent or greater extent than IFITM1." (PMID 27219333, 2016). "In agreement, we also see that both IFITM1 and IFITM3 can inhibit infection by SFV, when virus is fused at the cell surface." (PMID 27219333, 2016). "IFITM3‐HA also inhibited SFV infection via plasma membrane fusion in the P1‐ and P2‐ cells to a similar extent to that seen with IFITM1‐HA." (PMID 27219333, 2016). "The inability to up-regulate IFITM3 levels independently of infection or IFNs is a challenge preventing the field from harnessing the activity of IFITM3 for infection prevention." (PMID 26263374, 2015). "Heightened IFITM3 levels significantly protected NEDD4 knockout cells from infection by influenza A and B viruses." (PMID 26263374, 2015). "IFITM3 mRNA was quantified by qRT-PCR and the biological effect of the knockdown assessed by infection with influenza A/WSN/33." (PMID 25614588, 2015).
infection (continued). "Overall, our study identifies inhibition of NEDD4 as a novel strategy for preventing infection by influenza virus and other IFITM3-sensitive viruses through the increased accumulation of the antiviral restriction factor IFITM3." (PMID 26263374, 2015). "Overall, this work identifies the enzyme NEDD4 as a new therapeutic target for the prevention of influenza virus infections, and introduces a new paradigm for up-regulating cellular levels of IFITM3 independently of IFN or infection." (PMID 26263374, 2015). "Compared to the vector control transfection, both HA-IFITM3 and IFITM3 were able to significantly inhibit infection by influenza A virus (IAV) H1N1 strain PR8 as measured by anti-IAV nucleoprotein staining by flow cytometry." (PMID 26075508, 2015). "Interferon (IFN)-induced transmembrane protein 3 (IFITM3) is a 15 kDa protein that restricts cellular infection by influenza virus." (PMID 26263374, 2015). "Depleting NEDD4 from cells results in IFITM3 accumulation and greater resistance to infection by influenza viruses." (PMID 26263374, 2015). "Yet, even with this potent mechanism by which IFITM3 limits infections, influenza virus remains a significant health concern." (PMID 26263374, 2015). "The other DC subset contained in the lung mucosa, CD11b+ DC, were likewise protected from infection by IFITM3." (PMID 26600246, 2015). "Inhibition of virus yields was more profound following a low m.o.i. infection (>1 log10 for pig IFITM3 and >2 log10 for both microbat and human IFITM3) relative to control green fluorescent protein (GFP)-expressing cells." (PMID 25614588, 2015). "Expression of IFITM3 resulted in marked inhibition of PR8-NS1-Gluc infection in all cellular systems tested, in keeping with published results." (PMID 24842154, 2014). "In our research, we demonstrated that, like FL IFITM3, Δ21 IFITM3 and Y20A IFITM3 efficiently restrict infection of IAVs." (PMID 25314048, 2014). "IFITM3 has been shown to potently restrict infection by IAV and the Respiratory Syncytial Virus in vivo." (PMID 24699674, 2014). "We chose to focus on IFITM3 to study the mechanism of IAV restriction because this protein potently inhibits infection in vitro and in vivo." (PMID 24699674, 2014). "The chicken IFITM3 protein restricts cell infection by influenza A viruses and lyssaviruses to a similar level as its human orthologue." (PMID 24067955, 2013). "All of these human IFITM proteins have been shown to restrict viral entry and infection, with IFITM3 being generally thought to be the most potent." (PMID 23358889, 2013). "Together, these results improve our understanding of how IFITM3 serves to defend us against viral invasion at a very early stage of infection." (PMID 22046135, 2011). "IFITM3 inhibited infection by all influenza A virus strains tested including a 1968 pandemic isolate and two contemporary seasonal vaccine viruses." (PMID 22046135, 2011). "Depletion of IFITM3 fully restored IAV HA-mediated infection, an effect only modestly enhanced through suppression of IFITM1 expression." (PMID 21253575, 2011). "Additionally, HEK293T cells coexpressing TLR7 and IFITM3 presented altered infection rates, suggesting a complex relationship in which TLR7 can modulate the host antiviral response, potentially impacting the overall dynamics of hMPV infection." (PMID 40235933, 2025). "Upon MVA infection, the loss of STING hampered the expression of type I interferons (IFNs) and, in turn, interferon-stimulated gene 15 (ISG15) and interferon-induced transmembrane protein 3 (IFITM3)." (PMID 40981440, 2025). "In addition, human IFITM3 inhibits infection at endosomes but enhances virus fusion at the plasma membrane." (PMID 40464579, 2025). "Likely, in collaboration with IFITM3, which is dysregulated upon infection in DSK cells, STING may counteract MVA, particularly during the entry phase, by targeting viral particles for elimination through the endosomal pathway." (PMID 40981440, 2025).
infection (continued). "The colocalization of the virus with IFITM3 was observed at both 3 and 24 h post infection (hpi)." (PMID 40871241, 2025). "Third, IFITM3, whether basally expressed or induced by interferon, broadly restricts infection of human cells by potentially zoonotic influenza viruses, and this function was independent of viral receptor binding preferences." (PMID 39477971, 2024). "Here, we tested the hypothesis that deficiencies in the innate immunity protein, Interferon-Induced Transmembrane Protein 3 (IFITM3), facilitate interspecies infection and adaptation by influenza viruses." (PMID 39477971, 2024). "Similarly, Ifitm3 induction was lower in old mice (~2-fold) during infection relative to young mice (~5-fold)." (PMID 38911865, 2024). "In detail, CsH reduced the innate resistance mechanism against LV infection performed through the interferon-induced transmembrane protein 3 (IFITM3) constitutive inhibition of viral entry by degrading IFITM3, leading to significant improvement in gene transfer levels both in murine and human HSCs." (PMID 38920667, 2024). "Infection of microglia was associated with a sharp increase in CCL2 and CXCL10 chemokine gene expression and the activation of many type I interferon stimulated genes (MX1, ISG15, ISG20, IFI27, IFITM3 and others)." (PMID 38737767, 2024). "For example, the role of IFITM3 rs12252 with infection severity has been shown in several studies." (PMID 37323564, 2023). "With regard to SARS-CoV-2, the impact of IFITMs on infection remains unclear, but may depend on cellular localization, as indicated for IFITM3 in humans and mice." (PMID 37323564, 2023). "Infection was modestly reduced by recombinant overexpression of IFITM3, suggesting that the SFV entry step might be weakly restricted by IFITM3 under some conditions." (PMID 36851478, 2023). "Here, we considered that intrahepatic Fn1+Ifitm3+ classical monocytes may be a maker immune cell during the inflammation or infection after LT." (PMID 38143768, 2023). "Mice lacking Ifitm3 are more susceptible to infection by IAV, West Nile Virus (WNV), and a range of alphaviruses." (PMID 36435199, 2023). "Two recent studies suggest that mislocalised IFITM2 and IFITM3 promoted infection with SARS-CoV-2." (PMID 37111405, 2023). "The reduction in infection by both viruses was significant for IFITM3." (PMID 36851478, 2023). "Also, we again noted significant enhancement of infection in the presence of IFITM3, consistent with our PLV experiments." (PMID 36350154, 2022). "For example, IFITM3 was shown to play a critical role in the early phase of viral entry during influenza A infection by clustering on virus-containing endosomes and lysosomes a couple of hours after infection." (PMID 35854219, 2022). "Despite similar weight loss in IFITM3 KO mice, infection with PR8-miR133b/206 resulted in a modest, statistically significant benefit in terms of survival as compared to infection with PR8-miRctrl (median survival times of 10 days for PR8-miRctrl versus 12 days for PR8-miR133b/206)." (PMID 35544568, 2022). "Thus, we identified that direct infection of heart cells is required for cardiac dysfunction during influenza virus infection in IFITM3 KO mice." (PMID 35544568, 2022). "Intriguingly, mutants of human IFITM3 that lack the capacity to internalize into endosomes lost antiviral activity and promoted SARS-CoV-2 and MERS-CoV infection, revealing that IFITM3 can either inhibit or enhance infection depending on its subcellular localization." (PMID 33880473, 2022).